KDM6A (lysine demethylase 6A)
Description:
Histone demethylase that specifically demethylates 'Lys-27' of histone H3, thereby playing a central role in histone code. Demethylates trimethylated and dimethylated but not monomethylated H3 'Lys-27'. Plays a central role in regulation of posterior development, by regulating HOX gene expression. Demethylation of 'Lys-27' of histone H3 is concomitant with methylation of 'Lys-4' of histone H3, and regulates the recruitment of the PRC1 complex and monoubiquitination of histone H2A. Plays a demethylase-independent role in chromatin remodeling to regulate T-box family member-dependent gene expression (By similarity).
Synonyms: UTX; KABUK2; bA386N14.2
Tractability: Small molecule: a structure with a bound ligand is known; a high-quality ligand is known; it has a binding pocket of medium quality. PROTAC: ubiquitination databases record sites on it; its protein half-life has been measured; a small molecule that binds it is known.
Target class: Epigenetic regulator; Jumonji domain-containing; Eraser; Lysine demethylase
Chemical probes: GSK-J1, GSK-J4 (high quality), IOX1 (high quality)
Gene: Protein-coding gene on chromosome X (44,873,130 to 45,112,779, forward strand). Ensembl gene ENSG00000147050.
Subcellular location: Nucleus
Subcellular location (Human Protein Atlas): Nucleoli; Nucleoli rim; Nucleoplasm
Pathways (Reactome):
Gene expression (Transcription): Epigenetic regulation of gene expression by MLL3 and MLL4 complexes; Formation of WDR5-containing histone-modifying complexes; MLL4 and MLL3 complexes regulate expression of PPARG target genes in adipogenesis and hepatic steatosis
Developmental Biology: Activation of anterior HOX genes in hindbrain development during early embryogenesis; Chromatin modifications during the maternal to zygotic transition (MZT)
Chromatin organization: HDMs demethylate histones
Gene Ontology:
Molecular function: histone H3K27me2/H3K27me3 demethylase activity; protein binding; chromatin DNA binding; histone demethylase activity; RNA polymerase II cis-regulatory region sequence-specific DNA binding
Biological process: chromatin remodeling; heart development; regulation of gene expression
Cellular component: histone methyltransferase complex; MLL3/4 complex; nucleus; nucleoplasm
Gene-disease validity (ClinGen):
ClinGen rates the evidence that KDM6A causes each of these diseases.
Kabuki syndrome 2 (X-linked): Definitive.
Cancer hallmarks: proliferative signalling (promotes); invasion and metastasis (suppresses); invasion and metastasis (promotes)
Homologues: Orthologues: chimpanzee KDM6A (100% identical), macaque KDM6A (99% identical), pig KDM6A (99% identical), dog KDM6A (99% identical), rat Kdm6a (97% identical), rabbit KDM6A (94% identical), mouse Kdm6a (94% identical), tropical clawed frog kdm6a (88% identical), guinea pig KDM6A (77% identical), zebrafish kdm6a (74% identical), Drosophila melanogaster Utx (37% identical), Caenorhabditis elegans utx-1 (27% identical), and 3 more. Paralogues in human: UTY (86% identical), KDM6B (32% identical).
Diseases named in the same sentence as KDM6A in open-access papers:
KDM6A is named in the same sentence as 235 diseases in open-access papers, as found by Europe PMC text mining. Sharing a sentence is not in itself a finding about the gene and the disease. The quoted sentences say what the papers report.
Kabuki syndrome (81 papers, 2013 to 2026). Kabuki syndrome (KS) is a multiple congenital anomaly syndrome characterized by typical facial features, skeletal anomalies, mild to moderate intellectual disability and postnatal growth deficiency. "A few patients with Kabuki syndrome also exhibit KDM6A mutations, leading to abnormal facial features, skeletal malformations, and cardiac and cognitive impairments." (PMID 40297816, 2025). "KDM6A mutations have been implicated in congenital disorders such as Kabuki Syndrome, as well as in sex differences in development and cancer." (PMID 39754175, 2025). "We developed a DNA methylation signature for Kabuki syndrome 1 and found that a KDM6A variant causing Kabuki syndrome 2 had a disease-like classification score at Kabuki syndrome 1 signature sites." (PMID 37022461, 2024). "Subsequent studies have revealed that 9–14% of KMT2D-negative patients and <5% of patients with Kabuki syndrome presented with pathogenic variants in the KDM6A gene." (PMID 38667491, 2024). "Previously, the association of KDM6A with Notch signaling has been shown for neural crest cells in connection to Kabuki syndrome, as well as the reprogramming of germ line cells to neurons." (PMID 36980177, 2023). "presented a large cohort of KDM6A-caused Kabuki syndrome and a review of the literature yielding a prevalence in the overall cohort of 56% for neonatal hypoglycemia and 28% for hyperinsulinism." (PMID 37065762, 2023). "Kabuki syndrome (KS) is a rare multisystemic disease due to mutations in the KMT2D or KDM6A genes, which act as epigenetic modulators of different processes, including immune response." (PMID 37360370, 2023). "The Kabuki syndrome can be caused by the loss of function of KMT2D (also called MLL2) or KDM6A (also called UTX)." (PMID 35997367, 2022). "Few subjects also were tested for changes in KMT2D and KDM6A, the genes implicated in Kabuki Syndrome, as well as the epigenetic and genetic alterations of chromosome 11p15 implicated in Beckwith-Wiedemann Syndrome." (PMID 36389353, 2022). "Pathogenic variants in the genes encoding the chromatin modifiers KMT2D and KDM6A are responsible for Kabuki syndrome 1 (KS1) and Kabuki syndrome 2 (KS2), respectively." (PMID 35384273, 2022). "For example, Tier1 genes included KDM6A, a gene responsible for syndromic hearing loss (Kabuki syndrome 2; OMIM: 300827)." (PMID 35248088, 2022). "KDM6A mutations have been implicated in congenital disorders such as Kabuki Syndrome, as well as in sex differences in cancer." (PMID 35871105, 2022). "In this study, we use molecular mechanic and molecular dynamic simulations to enhance the annotation and mechanistic interpretation of the potential impact of eleven KDM6A missense variants found in Kabuki syndrome patients." (PMID 33546721, 2021). "On the other hand, KDM6A mutations are frequently found in individuals with Kabuki syndrome (KS), a genetic disease with developmental delay and congenital anomalies, highlighting the role of KDM6A in development." (PMID 33477877, 2021). "Kabuki syndrome is a rare disease which occurs about once in every 32,000 births and KDM6A mutations account for only ~ 5% of all cases." (PMID 33546721, 2021). "Epigenetic factors such as KMT2D and KDM6A are mutated in humans with Kabuki Syndrome, where a varying percentage of patients show cardiac defects." (PMID 34698193, 2021). "This study describes 5 novel variants of 7 KMT2D/KDM6A gene and summarizes the clinical manifestations and the mutational spectrum of 47 Chinese Kabuki syndrome (KS) patients." (PMID 31727177, 2019). "The histological finding of interlobular bile duct paucity and the genetic mutation in KDM6A, as well as several clinical findings consistent with Alagille syndrome or Kabuki syndrome, made it difficult to confirm the diagnosis of BA." (PMID 31414320, 2019). "The associated SNP at Xp11.3 was upstream from KDM6A, mutations in which are known to cause Kabuki syndrome." (PMID 28441456, 2017).
Kabuki syndrome (continued). "Mutations in MLL2 and KDM6A are also implicated in Kabuki syndrome, whilst mutations in CHD7 are implicated in CHARGE syndrome." (PMID 26188466, 2016). "Gene sequencing of KMT2D and KDM6A can be used to detect mutations in patients with a clinical diagnosis of Kabuki syndrome." (PMID 25896430, 2015). "Approximately 6 percent of Kabuki syndrome cases are caused by heterozygous mutation in lysine (K)-specific demethylase 6A (KDM6A)." (PMID 25750614, 2014). "KDM6A mutations have been discovered in patients with Kabuki syndrome, a rare syndrome associated with distinct facial features, intellectual disability, growth retardation, and skeletal anomalies." (PMID 23658530, 2013). "Mutations of KDM6A in human cause Kabuki syndrome, associated with growth retardation, unique facial features, and severe intellectual disability." (PMID 23658530, 2013). "Mutations in KMT2D, similar to those in KDM6A, are associated with Kabuki syndrome." (PMID 39941150, 2025). "Kabuki syndrome, caused by mutations in KDM6A or KMT2D, leads to developmental abnormalities." (PMID 39941150, 2025). "Therefore, extending our studies to human models will help determine the role of KDM6A in regulating X-linked gene expression in cases of sex chromosome aneuploidy as well as Kabuki syndrome and in cancer, where it is frequently mutated." (PMID 39754175, 2025). "Notably, there is convincing evidence of significant genotype-phenotype correlations with a higher prevalence of neonatal hypoglycemia and hyperinsulinism in patients with KDM6A-caused Kabuki syndrome." (PMID 37065762, 2023). "Importantly, KDM6A is mutated in Kabuki syndrome, leading to facial abnormalities and cognitive dysfunction." (PMID 36980177, 2023). "This suggests that – although the predisposition to hyperinsulinism applies to Kabuki syndrome, in general – the defect of KDM6A may more specifically impact β-cell function compared to a defect of KMT2D." (PMID 37065762, 2023). "Among the dysregulated genes are candidate genes that may explain abnormal developmental features of Kabuki syndrome caused by KDM6A mutations in human." (PMID 35871105, 2022). "Our identification of KO dysregulated genes involved in development, immune cell functions, neuronal cell functions, and metabolism may help further identify KDM6A targets implicated in Kabuki syndrome, a disorder with more severe phenotypes in males." (PMID 35871105, 2022). "Importantly, among the KDM6A targets common to both reciprocal crosses we identified a subset of genes associated with multiple phenotypes observed in individuals with Kabuki syndrome due to mutations in KDM6A in human." (PMID 35871105, 2022). "While our studies are performed in ES cells where developmental pathways are not fully represented, our data provide information on pathways and lineages that may be impacted in syndromes due to KDM6A mutations such as Kabuki Syndrome." (PMID 35871105, 2022). "Our study demonstrates that the KDM6A Kabuki syndrome variants may impair histone demethylase function through various mechanisms that include altered protein integrity, local environment, molecular interactions and protein dynamics." (PMID 33546721, 2021). "Kabuki syndrome is caused by a heterozygous mutation in the KMT2D or KDM6A genes." (PMID 29914387, 2018). "Recently, Yap et al21 described a cohort of 10 patients with pathogenic variants in KDM6A who presented with HH before receiving a diagnosis of Kabuki syndrome later in life suggesting that HH may be a more common presenting feature than previously recognized." (PMID 30238501, 2018). "At least 589 patients with Kabuki syndrome due to KDM6A mutations have been reported." (PMID 29914387, 2018). "Therefore, analyzing mutations in the KMT2D and KDM6A genes would help confirm the diagnosis in patients who fulfilled the clinical diagnostic criteria for Kabuki syndrome." (PMID 25896430, 2015).
Kabuki syndrome (continued). "Moreover, other research supported that KDM6A (UTX) may be the causative gene of Kabuki syndrome, an inherited disorder characterised by developmental delay and intellectual disability." (PMID 39779477, 2025). "However, by considering the structural and dynamics-based scores, we have identified many mechanisms by which these Kabuki syndrome variants may damage the function of KDM6A." (PMID 33546721, 2021). "Interestingly, two of the presented candidate genes, KMT2D and KDM6A (a methyltransferase and a demethylase, respectively), regulate the chromatin methylation status and they are both causes of Kabuki syndrome, whose wide spectrum of features includes also OFCs and TA." (PMID 27699475, 2016). "Kabuki syndrome, typically associated with KMT2D or KDM6A mutations, is characterized by distinct facial features, intellectual disability, and growth retardation." (PMID 41614934, 2026). "Distinct Facial Features & Intellectual Disability: Should prompt consideration of Kabuki syndrome (KMT2D/KDM6A), where diabetes arises from epigenetic dysregulation." (PMID 41614934, 2026). "For example, CHARGE syndrome driven by CHD7, and Kabuki syndrome driven by MLL2/KMT2D/KDM6A both demonstrate fetal ear developmental abnormalities." (PMID 41020230, 2025). "Kabuki syndrome is caused by mutations in the KMT2D gene, which encodes an H3K4 histone methylase that promotes active gene transcription, or in the KDM6A gene, an X-linked histone H3K27 demethylase." (PMID 39941150, 2025). "Among them, Kabuki syndrome is a syndromic DD/ID disorder characterized by a distinctive facial gestalt, caused by LoF pathogenic variants in the KMT2D and KDM6A genes." (PMID 40004505, 2025). "Some patients (3–8%) have pathogenic variants in KDM6A (OMIM # 300128), an X-linked gene which encodes lysine specific demethylase 6A and is defined as Kabuki syndrome 2 (KS2; OMIM # 300867)." (PMID 38206414, 2024). "In Kabuki syndrome, a multisystem disorder resulting in developmental abnormalities caused by mutations in KMT2D and KDM6A genes, approximately 60% of KMT2D mutations cause protein truncation resulting in loss of function." (PMID 37252797, 2023). "Beyond their roles in cancer and viral receptor expression, mutations in KDM6A and KMT2D have been identified in Kabuki syndrome, which is characterized by developmental delay." (PMID 37410700, 2023). "Kabuki syndrome (KS) is a rare neuro-developmental disorder caused by variants in genes of histone modification, including KMT2D and KDM6A." (PMID 36292647, 2022). "Kabuki syndrome is a rare genetic condition associated with two gene mutations: KMT2D in the majority of cases and KDM6A less frequently." (PMID 40041237, 2022). "Mutations of KDM6A and MLL4 cause Kabuki syndrome, a rare developmental disorder that exhibit systemic defects including craniofacial dysmorphism, growth retardation, and intellectual disability." (PMID 35481717, 2022). "Eleven Kabuki syndrome missense variants within the catalytic domain, along with five selected controls, were chosen and characterized for structure- and dynamics-based impact prediction to gain molecular insight into how these genetic variations may affect KDM6A protein function." (PMID 33546721, 2021). "Studies have shown that disruptions of the zebrafish orthologs, kmt2d and kdm6a, recapitulate phenotypes of Kabuki Syndrome." (PMID 34698193, 2021). "The genes involved in Kabuki syndrome, KMTD2 and KDM6A, which are affected by somatic inactivating variants in sporadic cancers, are an example of genes that were excluded based on this threshold." (PMID 34061292, 2021). "Kabuki syndrome (KS) is a rare disorder primarily associated with mutations in the KMT2D and KDM6A genes." (PMID 31179148, 2019). "Kdm6a is an homolog of the Y-linked gene Uty (T4 male TSS DO) and is related to the epigenetic mechanism of some immunological disorders, such as Kabuki syndrome (KS)." (PMID 31541153, 2019).
Kabuki syndrome (continued). "Kabuki syndrome is caused by mutations in the KMT2D (NM_003482.3, also known as MLL2, MLL4) or KDM6A (NM_021140.3) genes." (PMID 29914387, 2018). "A similar situation is found in Kabuki syndrome, which can result from loss-of function mutations in either the H3K4 MTase MLL2 or the H3K27 de-methylase KDM6A." (PMID 26188466, 2016). "Later, mutations in the KDM6A gene, which encodes a histone demethylase that interacts with KMT2D, were identified (Kabuki syndrome 2, OMIM 300867)." (PMID 25896430, 2015). "Similarly, there is a close resemblance between the DNAm signatures associated with pathogenic variants in ASXL2 and ASXL1 causing Shashi-Pena and Bohring-Optiz syndromes respectively, and between KDM6A and KMT2D variants causing Kabuki syndrome." (PMID 39843918, 2025). "It has been speculated that the loss of one copy of the KDM6A gene which is located on Xp might play a role, thus suggesting a similar mechanism for CHI as in KDM6A-related Kabuki syndrome." (PMID 37065762, 2023). "KDM6A and KMT2D are frequently mutated in Kabuki syndrome and multiple cancers." (PMID 37410700, 2023). "Kabuki syndrome (KS) is a Mendelian Disorder of the Epigenetic Machinery (MDEM) caused by loss of function variants in either of two genes involved in the regulation of histone methylation, KMT2D (34–76%) or KDM6A (9–13%)." (PMID 36276984, 2022). "Over the last 20 years, mutations in five key COMPASS complex genes have been linked to three human congenital syndromes: Kabuki syndrome (type 1 [KMT2D] and 2 [KDM6A]), Rubinstein-Taybi syndrome (type 1 [CBP] and 2 [EP300]), and Kleefstra syndrome type 2 (KMT2C)." (PMID 31924266, 2020). "Along with the chromatin regulators PHC1 (microcephaly) and KDM6A (Kabuki syndrome), another paradigmatic example is the ATP-dependent chromatin remodeler CHD8 (mSNC in enhancer), which controls neural progenitor cell proliferation through WNT-signaling related genes." (PMID 32299352, 2020). "Kabuki syndrome (KS) is a rare, multiple congenital anomaly syndrome demonstrating several distinctive clinical findings, and with identified gene mutations in KMT2D on chromosome 12 and KDM6A on chromosome X." (PMID 31414320, 2019). "KMT2D-related Kabuki syndrome (type 1) (OMIM# 147920) is inherited in an autosomal dominant manner and KMT2D mutations are present in 34–76 % of patients with KS, while KDM6A-related KS (type 2) (OMIM# 300867) is less frequent and inherited in an X-linked manner." (PMID 27699475, 2016). "Kabuki syndrome (KS) is a multiple congenital anomalies syndrome characterized by characteristic facial features and varying degrees of mental retardation, caused by mutations in KMT2D/MLL2 and KDM6A/UTX genes." (PMID 24633898, 2014). "Thus, a comprehensive screening of other genes associated with Kabuki syndrome (e.g., KDM6A, RAP1A, RAP1B, and HNRNPK) was not performed." (PMID 38667491, 2024). "Thus, we cannot rule out the possibility that KDM6A Kabuki syndrome variants have multifarious damaging effects beyond what we present in the current study." (PMID 33546721, 2021). "The aim of this study was to propose a new NGP model for predicting KS (Kabuki Syndrome) on 2D facial photographs and distinguish KS1 (KS type 1, KMT2D-related) from KS2 (KS type 2, KDM6A-related)." (PMID 38282012, 2024). "We first observed this when studying variants in the genes for Kabuki syndrome 1 [MIM: 147920] and Kabuki syndrome 2 [MIM: 300867], KMT2D [MIM:602113] and KDM6A [MIM: 300128], respectively." (PMID 37022461, 2024). "The role of KMT2D and/or KDM6A in the pathogenesis of Kabuki syndrome stems from a non-catalytic function in one or both of these proteins." (PMID 38857303, 2024).